HOMER3 (homer scaffold protein 3)
Diseases named in the same sentence as HOMER3 in open-access papers (continued):
Sharing a sentence is not in itself a finding about the gene and the disease.
tumor (6 papers, 2018 to 2023). "The expression of Homer2 was associated with tumor differentiation grade and TP level, Homer3 was related to tumor size, tumor nodes and GGT level." (PMID 33995622, 2021). "Moreover, a clear association was observed between HOMER3 at the cell membrane and high-grade tumours of stages T1 and higher (Ta vs ≥ T1: 5.3% vs 28.4%; p = 0.038) as well as lymph node metastasis (Ta vs MT; p = 0.05)." (PMID 34108014, 2021). "Correlation analysis results showed that Homer2 expression was significantly associated with tumor differentiation grade (P = 0.012) and TP (P = 0.032), while the expression of Homer3 was significantly related to tumor size (P = 0.010), tumor nodes (P = 0.026) and GGT level (P = 0.001)." (PMID 33995622, 2021). "Histological examination of the mice showed that low level of HOMER3 prevented H1299 cells from metastasizing to the lung and reduced the primary tumor burden." (PMID 38081871, 2023). "Based on the results of the protein interaction network analysis, we selected 17 proteins, that were previously reported to participate in tumor progression, as the potential targets to mediate the biological function of HOMER3." (PMID 38081871, 2023). "They further reported that under glucose deprivation and hypoxic conditions, HOMER3 contributed to the tumor cell’s invasive capacity." (PMID 35211123, 2022). "In our present study, we found the expression of both Homer2 and Homer3 were downregulated in HCC, which indicated a possible tumor suppressive role of Homer2 and Homer3 in HCC." (PMID 33995622, 2021). "Interestingly, the membrane/cytoplasm ratio increased with the stage of the disease (0.07 in Ta; 0.38 in T1; 0.33 in T2; 0.46 in T3; and 0.63 in T4), suggesting that the plasma membrane anchoring of HOMER3 could be a molecular feature associated with tumour aggressiveness." (PMID 34108014, 2021). "HOMER3 was also detected in 60% of the metastasis at the cell membrane, reflecting the percentage of positive primary tumours." (PMID 34108014, 2021). "According to our observations, hypoxia and glucose deprivation, two synergic events experienced by cancer cells as result of poor tumour vascularization, drive HOMER3 translocation to the cell membrane." (PMID 34108014, 2021). "HOMER3 promotes tumor aggressiveness and metastasis of TNBC cells via facilitating β-Catenin tyrosine phosphorylation." (PMID 33407765, 2021). "We started by observing that HOMER3 positive tumour areas co-localized with ST and STn antigens, suggesting close spatial proximity." (PMID 34108014, 2021). "Plasma membrane HOMER3 was observed in more aggressive primary tumours and distant metastases, being an independent predictor of worst prognosis." (PMID 34108014, 2021). "Having shown that ENO1 and Homer3 mediated cancer cell growth and metastasis induced by WBP2 overexpression, we explored the underlying mechanism of WBP2 acting as a key regulator of tumor development." (PMID 29497031, 2018). "Remarkably, recent studies reveal that HOMER3 is a potential tumor therapy target." (PMID 38081871, 2023). "We next explored whether peripheral blood expression level of Homer2 and Homer3 could be used to monitor tumor dynamics." (PMID 33995622, 2021). "In this study, our results show that HOMER3 is selectively overexpressed in TNBC and correlate earlier tumor metastasis and shorter patient survival." (PMID 33407765, 2021). "Therefore, we hypothesize that high level of HOMER3 in NSCLC may activate the expressions of downstream mitochondrial genes by GABPB1, thereby promoting mitochondrial anabolism, and creating the conditions for tumor proliferation and metastasis." (PMID 38081871, 2023). "Furthermore, while HOMER3 expression was not cancer-specific, STn and HOMER3 did not co-express in healthy tissue, suggesting that HOMER3-STn could be a tumor-specific biomarker that can be used to target the more aggressive cancer cell populations residing in the hypoxic TME." (PMID 35211123, 2022).
cancer (5 papers, 2018 to 2023). A tumor composed of atypical neoplastic, often pleomorphic cells that invade other tissues. "Using gene editing strategies, we have demonstrated that the presence of HOMER3 at the cell membrane significantly enhanced cancer cells proliferation and invasion by yet unknown molecular pathways, which should be identified in future studies." (PMID 34108014, 2021). "Moreover, it has identified HOMER3 as top-ranked targetable glycoprotein for targeting invasive cancer cells and metastases." (PMID 34108014, 2021). "Immunohistochemistry studies also suggest that STn and HOMER3 are not found together at the cell surface of healthy tissues, reinforcing the cancer-associated nature of the HOMER3-STn glycophenotype." (PMID 34108014, 2021). "Therefore, our observations strongly suggest that HOMER3 translocation to the cell surface may be a key event driving cancer aggressiveness." (PMID 34108014, 2021). "We evaluated the expression of ENO1 in several cancer cell lines and found that ENO1 and Homer3 were potent partners of WBP2 in U251 cells." (PMID 29497031, 2018). "In fact, observations arising from a wide array of healthy tissues strongly suggest that HOMER3 localization at the cell membrane is not common and may be characteristic of cancer cells." (PMID 34108014, 2021).
HOMER3 also shares sentences with these, for which no sentence is quoted: Acute Myelocytic Leukemia (1 paper); Alzheimer disease (1); Anxiety (1); autism (1); bile duct cancer (1); breast invasive carcinoma (1); COVID-19 (1); esophageal carcinoma (1); head and neck squamous cell carcinoma (1); hepatitis B (1); herpesvirus infection (1); Hypertension (1); lung adenocarcinoma (1); lung squamous cell carcinoma (1); non-small cell lung carcinoma (1); prostate carcinoma (1); schizophrenia (1).